NEU3 (neuraminidase 3)
Description:
Exo-alpha-sialidase that catalyzes the hydrolytic cleavage of the terminal sialic acid (N-acetylneuraminic acid, Neu5Ac) of a glycan moiety in the catabolism of glycolipids, glycoproteins and oligosaccharides. Displays high catalytic efficiency for gangliosides including alpha-(2->3)-sialylated GD1a and GM3 and alpha-(2->8)- sialylated GD3. Plays a role in the regulation of transmembrane signaling through the modulation of ganglioside content of the lipid bilayer and by direct interaction with signaling receptors, such as EGFR. Desialylates EGFR and activates downstream signaling in proliferating cells. Contributes to clathrin-mediated endocytosis by regulating sorting of endocytosed receptors to early and recycling endosomes.
Synonyms: SIAL3
Tractability: Small molecule: a high-quality ligand is known. Antibody: UniProt places it where antibodies can reach, with high confidence; its Gene Ontology location is reachable by antibodies, with high confidence. PROTAC: ubiquitination databases record sites on it; a small molecule that binds it is known.
Target class: Enzyme; Hydrolase
Gene: Protein-coding gene on chromosome 11 (74,984,361 to 75,018,893, forward strand). Ensembl gene ENSG00000162139.
Subcellular location: Cell membrane; Membrane, caveola; Early endosome membrane; Recycling endosome membrane; Lysosome membrane
Subcellular location (Human Protein Atlas): Nucleoplasm; Vesicles
Pathways (Reactome):
Metabolism: Glycosphingolipid catabolism
Metabolism of proteins: Sialic acid metabolism
Gene Ontology:
Molecular function: alpha-sialidase activity; exo-alpha-sialidase activity; protein binding
Biological process: carbohydrate metabolic process; ganglioside catabolic process; negative regulation of clathrin-dependent endocytosis; oligosaccharide catabolic process; positive regulation of epidermal growth factor receptor signaling pathway; glycosphingolipid catabolic process
Cellular component: early endosome membrane; lysosomal membrane; nucleoplasm; plasma membrane; recycling endosome membrane; cytoplasm; lysosome; membrane; caveola; external side of plasma membrane
Genetic constraint (gnomAD): Loss-of-function variants: 11 observed, 14.3 expected, observed/expected ratio (o/e) 0.77, 90% interval 0.48 to 1.27. The upper end of that interval is the gene's LOEUF score, 1.27, which puts it in group 5 of 6, group 1 being the genes least tolerant of losing a copy. Missense variants: 529 observed, 603.77 expected, observed/expected ratio (o/e) 0.88, 90% interval 0.81 to 0.94. Synonymous variants: 212 observed, 234.79 expected, observed/expected ratio (o/e) 0.9, 90% interval 0.81 to 1.01.
Homologues: Orthologues: chimpanzee NEU3 (99% identical), macaque NEU3 (92% identical), dog NEU3 (79% identical), pig NEU3 (76% identical), guinea pig NEU3 (70% identical), rabbit NEU3 (70% identical), mouse Neu3 (62% identical), rat Neu3 (55% identical), tropical clawed frog neu3 (44% identical), zebrafish neu3.1 (44% identical), zebrafish neu3.4 (41% identical), zebrafish neu3.2 (39% identical), and 2 more. Paralogues in human: NEU4 (40% identical), NEU2 (35% identical), NEU1 (23% identical).
Diseases named in the same sentence as NEU3 in open-access papers:
NEU3 is named in the same sentence as 73 diseases in open-access papers, as found by Europe PMC text mining. Sharing a sentence is not in itself a finding about the gene and the disease. The quoted sentences say what the papers report.
colon carcinoma (12 papers, 2012 to 2024). "In contrast, overexpression of ganglioside sialidase (Neu3) in colon carcinoma cells was associated with increased Bcl-2 and decreased caspase expression, which is another example of apoptosis suppression associated with GSLs metabolism." (PMID 38254878, 2024). "NEU3 overexpression in cancer cells in vitro, such as in colon cancer HT-29 cell line, has been tentatively linked to the EGFR-mediated signaling, LacCer accumulation, stimulation of cell growth, and inhibition of apoptosis." (PMID 31801289, 2019). "In the present study, however, we found that colon tumors still formed in mice in spite of the Neu3 deficiency." (PMID 22815940, 2012). "Here, to investigate the physiological role of NEU3 in tumorigenesis, we established Neu3-deficient mice and then subjected them to carcinogen-induced tumorigenesis, using a sporadic and a colitis-associated colon cancer models." (PMID 22815940, 2012). "To examine this possibility under physiological conditions, in the present study we generated Neu3-deficient mice and analyzed their susceptibility to tumorigenesis in carcinogen-induced models of sporadic and colitis-associated colon cancer." (PMID 22815940, 2012). "The DMH-treated Neu3-deficient mice developed colon tumors at an incidence (4/9, 44%) comparable to that of the wild-type mice (8/14, 57%)." (PMID 22815940, 2012). "Another example is a ganglioside-specific sialidase, namely, NEU3, which was upregulated in colon cancers, where enhanced NEU3 protected malignant cells against programmed cell death." (PMID 35563790, 2022). "Transfection of the NEU3 sialidase gene into colon cancer cells inhibited apoptosis and was accompanied by increased Bcl-2 and decreased caspase expression." (PMID 34064863, 2021). "In colon neoplasms, NEU3 mediates tumor cell proliferation through integrin-mediated signaling, depending on the extracellular matrix." (PMID 34683168, 2021). "In colon cancer cell lines, three of them sensitive to cetuximab in the absence of NEU3 overexpression and all sensitive to the drug after NEU3 transfection, we observed great variability." (PMID 33233823, 2020). "We previously revealed a requirement of cancer cells for NEU3 in vitro: the siRNA-mediated knock down of NEU3 induces the apoptosis of human cancer cells including colon cancer cell lines accompanied by suppression of the EGFR signaling pathway." (PMID 22815940, 2012). "The Neu3-deficient mice and the wild-type mice received a weekly injection of DMH for 20 weeks, and 4 weeks after the last injection, the mice were killed and examined for colon tumor incidence and size." (PMID 22815940, 2012). "NEU3 mRNA has been found to be highly increased in human colon cancer, in particular in the epithelial elements of adenocarcinoma, as compared with adjacent non-tumor mucosa; therefore, NEU3 might contribute to accumulation of LacCer in colon cancer." (PMID 31801289, 2019). "Such a potent increase of NEU3 expression is not unusual, but often seen in cancer compared with that in adjacent normal tissues, as we reported in the case of colon cancer." (PMID 25803810, 2015). "NEU4 was down-regulated in all EMT-induced cancer stem-like cells colon cancer cell lines DLD1, HT29 and LS174T, but not NEU1, NEU2 and NEU3." (PMID 30700826, 2019). "NEU3 is a degradation enzyme for sialyl Lewis X but not for sialyl Lewis A8, but NEU3 is expressed at much lower levels relative to NEU4 in all colon cancer cells." (PMID 30700826, 2019). "Moreover, several studies have shown that NEU3 is up regulated in most cancers, including melanoma, colon, renal, ovarian and prostate cancers NEU3 mRNA levels have been observed to increase 3- to 100-fold in human colon cancer tissues compared with adjacent non-tumour mucosal tissues." (PMID 29088281, 2017).
colitis (10 papers, 2012 to 2025). Inflammation of the colon. "Upregulation of NEU3 protein is associated with multiple diseases including intestinal inflammation and colitis, neuroinflammation, and lung fibrosis." (PMID 39570922, 2024). "Upregulation of NEU3 protein and increased desialylation of serum proteins is associated with multiple diseases including intestinal inflammation and colitis, rheumatoid arthritis, neuroinflammation, heart disease, and lung fibrosis." (PMID 39570922, 2024). "The host-encoded sialidase NEU3 has been shown to trigger colitis through the desialylation of intestinal alkaline phosphatase, which contributes to the detoxification of bacterial lipopolysaccharide." (PMID 36567940, 2022). "On the other hand, the Neu3-deficient mice were less susceptible than wild-type mice to the colitis-associated colon carcinogenesis induced by azoxymethane and dextran sodium sulfate." (PMID 22815940, 2012). "The physiological roles of the NEU3, including its specific function in colitis-associated colon carcinogenesis, remain important topics for future study." (PMID 22815940, 2012). "Two other preliminary experiments using small numbers of mice also suggested that Neu3-deficient mice had a decreased susceptibility to colitis-associated carcinogenesis." (PMID 22815940, 2012). "Thus underlying mechanism connecting Neu3-deficiency and reduced susceptibility to colitis-associated colon carcinogenesis remains to be elucidated." (PMID 22815940, 2012). "We found that Neu3-deficiency lowered the incidence of colitis-associated colon carcinogenesis." (PMID 22815940, 2012). "All the mice treated with AOM/DSS developed colon adenocarcinoma, but the number of adenocarcinomas per mouse was significantly lower in the Neu3-deficient mice than in the wild-type mice (p = 0.037), suggesting NEU3 is involved in colitis-associated colon carcinogenesis." (PMID 22815940, 2012). "Upregulation of neuraminidase 3 (NEU3) is associated with intestinal inflammation and colitis, neuroinflammation, and lung fibrosis." (PMID 39570922, 2024). "Neu3−/− mice are also protected from Salmonella enterica Typhimurium-induced intestinal inflammation and colitis, and colitis-induced colon cancer." (PMID 36613682, 2022). "Recurrent human food-poisoning by Salmonella enterica Typhimurium was shown to induce chronic intestinal inflammation in mice, leading to colitis onset, with mammalian Neu3 neuraminidase as the responsible factor for intestinal alkaline phosphatase desialylation and deficiency." (PMID 37582971, 2023). "Our present findings show that the loss of the Neu3 gene in mice lowered the incidence of colitis-associated colon carcinogenesis, whereas the loss had no apparent effect on tumor incidence or growth in a sporadic colon carcinogenesis model." (PMID 22815940, 2012). "Interestingly, abrogation of Neu3 prevented the development of severe colitis." (PMID 37582971, 2023). "This study also found that mice deficient in Neu3 were not protected from DSS-induced colitis, suggesting that other sialidases (which would be inhibited by exogenous Sia or pansialidase inhibitors) play an important role in the pathobiology of intestinal inflammation." (PMID 36719745, 2023).
pulmonary fibrosis (9 papers, 2017 to 2026). Chronic progressive interstitial lung disorder characterized by the replacement of the lung tissue by connective tissue, leading to progressive dyspnea, respiratory failure, or right heart failure. "In the mouse bleomycin model of pulmonary fibrosis, NEU3 is both necessary and sufficient for pulmonary fibrosis." (PMID 41827838, 2026). "The finding that NEU3 was elevated in patients with idiopathic pulmonary fibrosis led to study of its potential role in NAFLD." (PMID 40943651, 2025). "Some patients with idiopathic pulmonary fibrosis (IPF) have abnormally high levels of NEU3, which can upregulate active serum TGF-β1." (PMID 40943651, 2025). "Patients with pulmonary fibrosis have increased desialylation of some serum proteins, and elevated serum levels of NEU3." (PMID 39570922, 2024). "Consistent with this, pulmonary fibrosis was strongly attenuated in bleomycin-induced Neu3 knockout mice." (PMID 38500102, 2024). "In this paper and our previous work, we report a TGF-β1/DDX3/NEU3 /TGF-β1 positive feedback loop and show that inhibiting either DDX3 or NEU3 reduces lung fibrosis in bleomycin-treated mice." (PMID 36821384, 2023). "Genetic deletion of NEU3 or inhibiting NEU3 inhibits pulmonary fibrosis in mice, and DDX3 inhibitors inhibit TGF-β1–induced upregulation of NEU3 in lung fibroblasts." (PMID 36821384, 2023). "We observed increased levels of NEU3 protein in fibrotic lesions in human and mouse pulmonary fibrosis." (PMID 36613682, 2022). "Mass spectrometry showed that NEU3 desialylates SAP, suggesting that one way that elevated NEU3 in pulmonary fibrosis potentiates fibrosis is by desialylating the endogenous anti-fibrotic protein SAP." (PMID 36613682, 2022). "This indicates that NEU3 is necessary for the full spectrum of bleomycin-induced pulmonary fibrosis." (PMID 35999554, 2022). "There is extensive desialylation of glycoconjugates and upregulation of the sialidase NEU3 in the fibrotic lesions of patients with pulmonary fibrosis and mice with bleomycin-induced pulmonary fibrosis." (PMID 36613682, 2022). "Second, the extracellular sialidase NEU3 appears to be both necessary and sufficient for pulmonary fibrosis in mice." (PMID 36613682, 2022). "We also observed increased levels of NEU2 and NEU3 in mouse and pulmonary fibrosis, and observed that TGF-β1 can increase NEU2 and NEU3 in PBMC, and NEU3 in epithelial cells and fibroblasts." (PMID 29118338, 2017). "For pulmonary fibrosis, a positive feedback loop where elevated NEU3 causes upregulation of the profibrotic extracellular signals TGF-β1 and IL-6, and TGF-β1 and IL-6 upregulate NEU3, appears to participate in fibrosis." (PMID 39570922, 2024). "Genetic ablation of NEU3 or pharmacological inhibition of NEU3 reduces lung fibrosis in mice." (PMID 39570922, 2024). "Together, this suggests that NEU3 upregulation potentiates pulmonary fibrosis in mice." (PMID 36821384, 2023). "Mice lacking NEU3 essentially do not develop fibrosis in the bleomycin model, and aspiration of mouse NEU3 (but not enzyme-dead NEU3) causes pulmonary fibrosis in mice." (PMID 36821384, 2023). "We previously observed that the BALF from fibrotic lungs, and fibrotic lesions from human and mouse lungs, have elevated levels of NEU3, that NEU3 inhibitors attenuate bleomycin-induced pulmonary fibrosis, and that Neu3−/− knockout mice are resistant to bleomycin-induced inflammation and fibrosis." (PMID 35999554, 2022). "Despite these sex differences, our results indicate that NEU3 potentiates pulmonary fibrosis." (PMID 35999554, 2022). "Fourth, a variety of NEU3 inhibitors block pulmonary fibrosis in a mouse model." (PMID 36613682, 2022). "For unknown reasons, one bleomycin-treated mouse also showed anti-NEU3 staining of a band with an apparent molecular mass higher than NEU3 Together, these data indicate that the levels of some sialidases are increased in lung fibrosis in humans and mice." (PMID 29118338, 2017).
pulmonary fibrosis (continued). "We found that DDX3 was upregulated in the fibrotic lesions in patients with pulmonary fibrosis, and inhibiting DDX3 in fibroblasts reduced TGF-β1 upregulation of NEU3 levels." (PMID 36821384, 2023). "In the mouse bleomycin model of pulmonary fibrosis, injections of the DDX3 inhibitor RK-33 potentiated survival and reduced lung inflammation, fibrosis, and tissue levels of DDX3, TGF-β1, and NEU3." (PMID 36821384, 2023). "The extracellular sialidase neuraminidase 3 (NEU3) is upregulated in fibrotic lesions in IPF patient lungs and the lungs of mice with bleomycin-induced pulmonary fibrosis." (PMID 36821384, 2023). "We previously found that injections of the general sialidase inhibitor DANA, injections of the NEU3 inhibitor 2AP, or the lack of NEU3 attenuate bleomycin-induced pulmonary fibrosis in male mice." (PMID 39570922, 2024). "In the bleomycin model of pulmonary fibrosis, treatment with the DDX3 inhibitor RK-33 potentiated survival, attenuated inflammation and fibrosis, and reduced lung tissue levels of DDX3, TGF-β1, and NEU3 in young male mice." (PMID 36821384, 2023). "In the bleomycin model of pulmonary fibrosis, mice lacking NEU3 (Neu3−/−) showed strongly attenuated bleomycin-induced weight loss, lung damage, inflammation, and fibrosis." (PMID 35999554, 2022). "We previously found that injections of DANA or the lack of NEU3 both attenuate bleomycin-induced lung fibrosis in mice." (PMID 33378413, 2020). "Pulmonary fibrosis is potentiated by a positive feedback loop involving the extracellular sialidase enzyme neuraminidase 3 (NEU3) causing release of active TGF-β1 and TGF-β1 upregulating NEU3 by increasing translation without affecting mRNA levels." (PMID 36821384, 2023). "In a mouse model of pulmonary fibrosis, RK-33 reduced bleomycin-induced lung inflammation and fibrosis, and lung tissue levels of DDX3, TGF-β1, and NEU3, suggesting that the TGF-β1 upregulation of the translation pathway may be a viable target to inhibit fibrosis." (PMID 36821384, 2023). "The lungs from both preclinical models of lung fibrosis and patients with IPF have increased levels of sialidase activity in the bronchoalveolar lavage fluid (BALF), increased levels of NEU3 in the BALF, and increased levels of both NEU1 and NEU3 in the lung tissue." (PMID 35999554, 2022). "Inactive NEU3 did not enhance bleomycin-induced lung fibrosis." (PMID 35999554, 2022).
atherosclerosis (7 papers, 2019 to 2026). A disease characterized by the build-up of fatty material and calcium deposition in the arterial wall resulting in partial or complete occlusion of the arterial lumen. "In this study, NEU1-deficient (CathAS190A‐Neo), Neu3−/− or Neu4−/− mice were crossed with Apoe−/− mice, and atherosclerosis was evaluated." (PMID 36157440, 2022). "Targeting SP3/NEU3 seems to be a potential therapeutic strategy for such diseases with Neu5Ac accumulation like atherosclerosis (AS)." (PMID 42117319, 2026). "The sialidase genes NEU1 and NEU3 were found upregulated in the cardiovascular disease models, whereas disrupting NEU1 and NEU3 in mice attenuates atherosclerosis, cardiac hypertrophy, and cardiac fibrosis." (PMID 39596031, 2024). "It was found that either 90% reduction in Neu1 activity or complete inactivation of Neu3 in Apoe(-/-) animals slowed down the progression of atherosclerosis." (PMID 34070542, 2021). "In cardiovascular disease models, both NEU1 and NEU3 are upregulated, and genetic disruption of NEU1 or NEU3 in mice, or treatment of mice with sialidase inhibitors, attenuate atherosclerosis, cardiac hypertrophy, or cardiac fibrosis." (PMID 36613682, 2022). "However, increased NEU3 activity may also contribute to plaque instability in atherosclerosis." (PMID 31521172, 2019).
Insulin resistance (6 papers, 2012 to 2022). Increased resistance towards insulin, that is, diminished effectiveness of insulin in reducing blood glucose levels. "A study showed that obese mice with hypoxia induce insulin resistance through the HIF-2α-NEU3-ceramide pathway." (PMID 35190756, 2022). "In addition, NEU3 downregulation in the liver and muscle of aged mice led to insulin resistance, due to an increase in GM3 levels." (PMID 31013778, 2019). "Furthermore, in transgenic mice showing insulin resistance, NEU3 overexpression induced increases in the abundances of GM1 and GM2 in several tissues, including liver." (PMID 26338710, 2015). "The relationship between insulin resistance and intestinal hypoxia was explained, in part, by the activation of hypoxia-inducible factor-2α (HIF-2α) in hypoxic, HFD-fed mice leading to NEU3 activation." (PMID 35479093, 2022).